RNU6-140P (RNA, U6 small nuclear 140, pseudogene)
Gene: Small nuclear RNA gene on chromosome 19 (38,797,002 to 38,797,109, reverse strand). Ensembl gene ENSG00000207296.
Homologues: Orthologues: chimpanzee U6 (96% identical), dog U6 (94% identical), pig U6 (94% identical), rat U6 (90% identical). Paralogues in human: RNU6-246P (94% identical), RNU6-25P (94% identical), RNU6-33P (94% identical), RNU6-35P (94% identical), RNU6-1 (93% identical), RNU6-116P (93% identical), RNU6-2 (93% identical), RNU6-3P (93% identical), RNU6-48P (93% identical), RNU6-4P (93% identical), RNU6-5P (93% identical), RNU6-6P (93% identical), and 1290 more.